HIF1A (hypoxia inducible factor 1 subunit alpha)
Diseases named in the same sentence as HIF1A in open-access papers (continued):
Sharing a sentence is not in itself a finding about the gene and the disease.
cancer (continued). "The ERBB3 mutant protein (ERBB3 N418Q) blocked HIF-1α and NRF2 accumulation by inhibiting PI3K-AKT signaling activation, which resulted in the suppression of cancer growth and migration." (PMID 38424190, 2024). "The altered expression of ANG 1/ANG 2, influenced by HIF-1α-induced VEGF, marks the initiation of the “angiogenic switch,” contributing to aberrant angiogenesis in cancer patients." (PMID 38542288, 2024). "Inhibiting HIF1α activity can disrupt the expression of GLUT5 and other key metabolic regulators, impairing the metabolic adaptability of cancer cells." (PMID 39107723, 2024). "The downregulation of Wnt1 expression and its downstream factors, including β-Catenin/HIF-1α-mediated glycolysis, indicates the intricate mechanism by which XHP disrupts cancer cell metabolism and progression." (PMID 38994113, 2024). "In contrast, under hypoxic conditions, hypoxia-inducible factor 1 subunit alpha (HIF1A, also known as HIF1α) promotes ferroptosis resistance in several cancer cell lines." (PMID 38844964, 2024). "By destabilizing HIF1α, SMURF2 disrupts the hypoxic adaptation mechanisms of cancer cells, thereby reducing their survival advantage and possibly enhancing the efficacy of existing treatments." (PMID 39697237, 2024). "CCL2 produced by omental adipocytes binds to CCR2, activating the PI3K/Akt/mTOR pathway and its downstream effectors HIF-1α and VEGF-A, promoting migration and omental metastasis in cancer cells." (PMID 39408927, 2024). "In addition, via interactions with factors such as NF-kB, ERK 1/2, and HIF1-α, SP/NK-1R axis activation leads to transformation to the more mobile and invasive phenotype of cancer cells, resulting in cancer invasion and metastasis in numerous cancers, including HNCs." (PMID 39906323, 2024). "This suggests that these miRNAs affect cancers via their activity to either induce or suppress the expression of SP1, MYC, and HIF1A." (PMID 39590335, 2024). "To understand the mechanism behind this observation, we investigated the activation of Snail and Slug, two transcription factors that are regulated by HIF-1α expression under hypoxia and promote EMT in cancer cells." (PMID 38402183, 2024). "The pro-cancer gene HIF1A contains ARE motifs in its 3′UTR, which is critical for ZFP36L1 to directly interact with the 3ʹUTR of HIF1A mRNA and mediate HIF1A mRNA destabilization." (PMID 39547416, 2024). "The convergence of HIF-1α and EPO/EPOR signaling further underscores their complex influence on cancer progression." (PMID 38542288, 2024). "Disruptions in the HIF-1α/SMURF2 axis can impair these processes, providing potential targets for improving cancer treatments and overcoming resistance to existing therapies." (PMID 39697237, 2024). "Intensive ROS scavenging, including peroxiredoxin 1 (PRDX1), SOD2, CAT, GSH-PXs, thioredoxins (TRXs), and GSH, can be upregulated by the activation of TNFα, Nrf2, HIF1α, AMPK, and PGC1α, protecting cancer cells from damage and subsequent cell death." (PMID 38474405, 2024). "Previously, crosstalk between c-Met and other kinases or proteins, including Src, HIF-1α, PKB, and ERK-1/2, in cancer cells has been postulated." (PMID 38474118, 2024). "Injury-induced populations were highest for TFs related to cell proliferation, self-renewal, and cancer involving both intrinsic (E2F family, MYC, and ZFX) and extrinsic (HIF1a, EPAS1/HIF2a, NFYB, LEF1, GLI2, VDR, and SMAD1/3/5) pathways." (PMID 38905342, 2024). "To validate our findings, we recruited a cohort of 21 cancer patients for histological confirmation, revealing significant mRNA upregulation of STAT3, IL6, MMP9, MMP3, TGFB1, VEGF and HIF1A, coupled with downregulation of LHPP and PCK1, PTEN and BLC2." (PMID 39468431, 2024). "Given the critical role for angiogenesis in cancers, this study aimed to decipher the role and mechanism for LUBAC in HIF1α linear ubiquitination, stability, angiogenesis and tumorigenesis." (PMID 38272870, 2024).
cancer (continued). "One key player in hypoxia is hypoxia-inducible factor 1-alpha (HIF-1α), which allows cancer cells to survive in a low-oxygen environment and is associated with radioresistance." (PMID 39791719, 2024). "Further investigation of how ISO targets key molecules and pathways such as HIF1a signaling and the PI3K/AKT/mTOR pathway to facilitate its cancer inhibitory effects, is necessary for maximizing its effectiveness as a cancer therapeutic drug." (PMID 38339062, 2024). "While promising, the strategic targeting of the SMURF2-HIF1 pathway in cancer therapy confronts formidable hurdles due to the intricate roles and broad biological activities of SMURF2 and HIF1α." (PMID 39697237, 2024). "We selected three HIF-1α downstream genes (GLUT-1, CA9 and VEGF) since their overexpression is known to contribute to cancer progression through various mechanisms including metabolism reprogramming (for GLUT-1 and CA9) and angiogenesis (for VEGF)." (PMID 39458615, 2024). "HIF-1α has the ability to attach to hexokinase II and VDAC1, giving cancer cells resistance to apoptosis." (PMID 38737905, 2024). "Adaptation to hypoxia has been found to typically lead to HIF‐1α overexpression and mediate Gln catabolism through the downregulation of MYC expression in diverse cancer types, including glioma, CC, EC, BC, and ovarian cancer." (PMID 38721006, 2024). "Glucose 6-phosphate dehydrogenase is directly transactivated by HIF-1α and interacts with VEGF in cancer cells, linking PPP activation to angiogenesis." (PMID 38542288, 2024). "For example, PX-478 was tested in a Phase I dose-escalation study involving cancer patients (NCT00522652), demonstrating effective inhibition of HIF-1α and a reasonable safety profile." (PMID 39450110, 2024). "The stabilization of HIF-1α leads to the expression of glycolytic enzymes and glucose transporters, such as GLUT1 and LDHA, enhancing glycolysis and glucose uptake—hallmarks of cancer cell metabolism." (PMID 39408832, 2024). "Due to the all-line inhibition effects of MLN4924 on the neddylation pathway, pro-cancer factors such as PD-L1, ASCT2, and HIF-1α inevitably accumulate in cancer cells." (PMID 39062453, 2024). "KITENIN expression is associated with MAPK signaling and the AP-1 axis, and knockdown of KITENIN downregulates markers of cyclin D1, COX2, MMP3 and ERK1/2, HIF-1A, EMT, stemness and aerobic glycolysis, suppressing cancer progression." (PMID 39030594, 2024). "Among these, ALDOA induces the expression of hypoxia-inducible factor-1α (HIF-1α), leading to typical EMT-like morphological changes in cancer cells, including a transition from cuboid to spindle shape and loss of microvilli." (PMID 38577616, 2024). "Beyond traditional chemotherapy, cetuximab, an anti-EGFR monoclonal antibody, counteracts the Warburg effect by inhibiting HIF-1α regulated lactate dehydrogenase A (LDH-A), thus, disrupting the metabolic reprogramming that promotes cancer cell survival." (PMID 39169426, 2024). "Numerous anti-cancer factors and pro-cancer factors are directly modified by NEDD8, and certain neddylation substrates such as CRL, EGR1, and HIF-1α can simultaneously regulate both types of factors." (PMID 39062453, 2024). "FBW7 deletion promotes HIF-1α accumulation, while FBW7 overexpression ubiquitinates and degrades phosphorylated HIF-1α, thus regulating angiogenesis in cancer." (PMID 37470788, 2024). "Meanwhile, it was shown by several systems analyses that SP1, HIF1A, and MYC functioned as master regulators of cancer development." (PMID 39590335, 2024).
cancer (continued). "HIF, a heterodimeric complex composed of a regulated subunit (e.g., HIF-1α and HIF-2α) and a constitutive subunit (HIF-1β), is a major regulatory protein facilitating cancer cell colonization." (PMID 39273055, 2024). "Several signaling pathways have been identified as upstream regulators for activation of EMT in cancers, including Wnt, Notch, TGFβ, PI3K/AKT/mTOR, JAK/STAT, and hypoxia/HIF-1α signaling pathways." (PMID 38792011, 2024). "Recent studies have highlighted HIF1α as a key regulator of GLUT5 expression, linking it to the metabolic reprogramming observed in cancer cells." (PMID 39107723, 2024). "Recent studies have highlighted the complex interactions between CDK4/6, HIF1α, and SMURF2, particularly in regulating HIF1α stability, which has significant implications for cancer progression." (PMID 39697237, 2024). "Key immunotherapy approaches that can be combined with HIF-1α targeting include checkpoint inhibitors, CAR T-cell therapy, and cancer vaccines." (PMID 39493156, 2024). "As a major member of HIF-1α signaling pathway, it has been proved that PGK1 is directly regulated by HIF-1α in many cancers." (PMID 39695074, 2024). "The critical role of HIF1α and VEGF as biomarkers for aggressive cancer phenotypes highlights the therapeutic importance of targeting these pathways." (PMID 39697237, 2024). "These marker genes play diverse roles in cancer, such as promoting growth and proliferation (MYC, HIF1A, ATM), inhibiting apoptosis (MCL1, BIRC3, BCL2) and facilitating invasion (CXCR4, CD55)." (PMID 38982317, 2024). "22d also showed a significant downregulation of HIF-1α, EPAS-1(HIF-2α), and carbonic anhydrase IX (CA-IX), all proteins involvedin several hallmarks of cancer." (PMID 38261767, 2024). "PTEN modulates HIF-1α expression through PTEN/p-Akt signaling, suppressing VEGF expression and angiogenesis across various cancer types." (PMID 39063014, 2024). "In line with in silico, in vitro studies showed that a significant pattern of reduction or suppression of HIF-1A, EGFR tyrosine kinase, and HER2 was observed in MCF-7 cancer cells given EAE treatment (p < 0.05)." (PMID 38474594, 2024). "In preclinical models, inhaled anesthetics have been shown to upregulate HIF-1α and VEGF, promoting angiogenesis and cancer cell survival." (PMID 39766169, 2024). "Epigallocatechin isolated from this extract downregulated LDH-A expression, a feature of cancer cells, and accelerated HIF-1a cochaperone proteasome degradation by interfering with the complex HSP90/HIF-1a." (PMID 38791506, 2024). "We also found inhibition of HIF‐1α protein expression and VEGF secretion in cancer cells following treatment with GP‐2250 in vitro." (PMID 39114948, 2024). "In summary, lactate secreted by cancer cells can promote the transformation of fibroblasts into iCAFs and the expression of CXCL12, possibly via the PI3K-Akt-HIF1A axis." (PMID 38287007, 2024). "In certain cancer models, miR-25 has been shown to stimulate angiogenesis by targeting prolyl hydroxylase domain protein 1 (PHD1), a negative regulator of HIF-1α." (PMID 39769102, 2024). "Melittin inactivated the YAP/HIF-1α pathway via up-regulation of LATS2, ultimately inhibiting cancer progression of NSCLC." (PMID 38889502, 2024).
cancer (continued). "The transcriptomic and functional analyses reveal that the downregulation of three genes (HIF1A, COPS5, and RPS3) largely contributes to cancer resistance in MPI." (PMID 38360878, 2024). "PKM2, a key player of the Warburg effect which is induced by HIF-1α, and STAT3 acts as HIF-1α/PKM2 feed-back loop participants which in turn enhances the Warburg effect in cancer." (PMID 38245798, 2024). "The proto-oncogene AKT has also been shown to modulate HIF-1α and VEGF protein expression through the PI3K/PTEN/AKT/FRAP pathway in cancer cells." (PMID 39055895, 2024). "The HIF-1α stimulation of FGF signaling plays a critical role in embryonic development, tissue repair, and cancer progression." (PMID 38542288, 2024). "So far, we have presented several pieces of evidence to support the concept that SP1, HIF1A, and MYC collaborate to promote cancer development and that inhibitors of these transcription factors should induce strong anticancer activity." (PMID 39590335, 2024). "HIF-1α and HIF-2α are frequently overexpressed in cancer tissues, resulting in the progression of tumors, resistance to chemotherapy and radiation, and a poor prognosis." (PMID 38766303, 2024). "The dysregulated proliferation observed in OSCC cancer cells initiates a series of events, including the overabundant expression of angiogenic factors such as VEGF and HIF-1α." (PMID 39124760, 2024). "Higher expression of HIF1A, ABCA1, FPR1, CD63, and FCN1 was found in cancer compared to healthy state." (PMID 39315092, 2024). "At the molecular level, NDQ lowers cancer biomarkers, CEA, and HIF-1α, as well as the VEGF and MMP-9 metastatic biomarkers." (PMID 39474040, 2024). "While HIF1α is a well-established factor in cancer biology, this review article focuses on the intricate interplay between SMURF2 and HIF1α." (PMID 39697237, 2024). "In a different study, in TNBC models including MDA-MB-231 cells, MYC and MCL1 were found to cooperatively promote paclitaxel-resistant cancer stem cells by increasing OXPHOS, reactive oxygen species (ROS) production, and HIF-1α expression." (PMID 38579004, 2024). "Albendazole down regulates HIF-1α in non-small cell lung cancer (NSCLC) cells, inhibiting glycolytic enzymes and lactate formation and thereby curbing cancer proliferation." (PMID 39683818, 2024). "As a result, HIF-1α is translocated to the nucleus where it binds HIF-1β to transcribe a myriad of genes involved in adaptation to hypoxia and cancer progression." (PMID 38341408, 2024). "By reducing HIF1α levels, SMURF2-mediated degradation disrupts key adaptive responses in tumors, such as angiogenesis and metabolic reprogramming, both essential for cancer cell survival in hypoxic conditions." (PMID 39697237, 2024). "Thus, the regulation of HIF-1α could serve as a potential approach for treating cancer cells." (PMID 38792080, 2024). "For example, the lncRNA-p21 functions as a hypoxia-dependent lncRNA that disrupts the binding of HIF-1α to VHL, subsequently stabilizing HIF-1α and promoting glycolysis in cancer cells." (PMID 38481809, 2024). "As research on HIF-1α deepens, the potential use of HIF inhibitors in cancer therapy has gained increasing interest." (PMID 39766299, 2024). "Under hypoxic conditions, transforming growth factor β (TGF-β) also participates in the HIF-1α signalling pathway and increases the level of PD-L1 in HPV-driven cancers." (PMID 39735605, 2024). "Other important cancer-related molecules and pathways were inhibited upon GCV treatment, for example, HIF1A, MAP2K1/2, PI3K, JUN, and HDAC." (PMID 38927982, 2024). "HIF‐1A and CCL2 have been shown to play a pivotal role in the recruitment of monocytes and cancer progression; however, the interrelationship between these two factors varies in solid tumor types." (PMID 35658112, 2024). "Previous reports have suggested HIF1α to be a target of deacetylation by SIRT1 at Lys 674, which contribute to metabolic reprogramming in cancer cells." (PMID 39693143, 2024).
cancer (continued). "In ovarian cancer, LPA secreted from cancer cell induces aerobic glycolysis reprogramming via NOX1, ROS and HIF1α." (PMID 39075612, 2024). "Preoperative serum HIF-1α, HIF-2α and YKL-40, especially the combination of HIF-1α and YKL-40, have a predictive value for the degree of VInv and cancer recurrence in FTC patients." (PMID 39277981, 2024). "Subsequently, the expression of both HIF-1α and ABCG2 was decreased by miR-519c, resulting in the decrease of GLUT1 expression as well as cancer cell metabolism under hypoxia." (PMID 39479443, 2024). "We thus pinpointed two enriched metabolic pathways, central carbon metabolism in cancer and HIF-1 signaling pathways including 9 out of 12 genes considered as HIF-1A downstream targets." (PMID 39567394, 2024). "All three proteins, HIF-1α, ANG-2, and IL-1β, are widely studied in the literature as biomarkers of various cancer diseases." (PMID 39275392, 2024). "In conclusion, CARM1 is a potential cancer biomarker and CARM1, HIF1A, and CDK4 are positively correlated in multiple cancers." (PMID 38476024, 2024). "Similarly, in the CML cell line K562, HIF-1α could strengthen the invasiveness of cancer cells by elevating the level of glycolysis in response to the knockdown of fumarate hydratase (FH) expression, while also entailing a reduced ability to repair DNA after damage." (PMID 37588219, 2024). "CCND1 (Cyclin D1), MPP2 (Membrane palmitoylated protein 2), Bax, Bcl2, HIF1A and VEGFA are transcriptionally regulated molecules that are related to cell proliferation, apoptosis and cancer cell invasion and metastasis processes." (PMID 39834948, 2024). "The targets for HIF-1α include LDH-A, PFKFB3, PDK-1, and PDK-3; therefore, the expression and activities of these proteins are increased in cancer cells." (PMID 38339256, 2024). "The functions of HIF1α and SMURF2 across different cancer types highlight their significance as therapeutic targets." (PMID 39697237, 2024). "QUE can control HIF-1α, which re-sensitizes 4T1 cells, MCF-7/Dox cells, and HCT116 cancer cells to DDP and etoposide." (PMID 38572428, 2024). "For example, cardiac glycosides have been used as HIF-1α inhibitors, reducing proliferation and inducing autophagy and/or apoptosis in cancer cells; or LBH589, a panobinostat that also reduces HIF-1α and VEGF levels." (PMID 38341408, 2024). "Hypoxia-induced HIF-1α and HIF-2α have a promoting effect on the expression of ABC transporters, including ABCB1, ABCB5, ABCC1, and ABCG2, and induce drug resistance in cancer cells." (PMID 38725864, 2024). "M4N also decreases the cellular content of HIF1A, another major transcription factor, in cancer cells under hypoxia, indicating that it functions as a dual inhibitor of both SP1 and HIF1A." (PMID 39590335, 2024). "Human Apoptosis Array analysis demonstrated IATL’s influence on HIF-1α and TNF R1 expression, implicating its role in cancer cell growth and death regulation." (PMID 39382942, 2024). "HIF-1α and HIF-2α have distinct expression patterns and functions, which play important roles in cancer development." (PMID 39273055, 2024). "Nevertheless, all of the inhibitors against SP1, HIF1A, or MYC can be considered potential anticancer drugs due to the nature of these TFs as master regulators of cancer." (PMID 37998757, 2023). "Interestingly, c-Myc, n-Myc and Hif-1α were the three top-ranked TFs with the highest number of predicted binding sites, in line with the notion that c-Myc overexpression in various cancers positively modulates the expression of genes involved in glucose metabolism." (PMID 37198319, 2023). "SFN also inhibited cancer cell invasion and decreased the expression of pro-angiogenic markers (VEGFA, VEGFR2, HIF-1α, and eNOS) in both iCCA cell lines." (PMID 36899823, 2023). "This included the HIF-1α inhibitor BAY 87–2243, which is in phase 1 clinical trials for cancer, as well as the FDA-approved antioxidant octyl gallate." (PMID 36536241, 2023).